MYC (MYC proto-oncogene, bHLH transcription factor)
Diseases named in the same sentence as MYC in open-access papers (continued):
Sharing a sentence is not in itself a finding about the gene and the disease.
T-cell lymphoma (51 papers, 2005 to 2025). "This is the case of MYC-driven B- and T-cell lymphoma models, where MNT deficiency impairs MYC-driven tumorigenesis." (PMID 33419981, 2021). "Eμ-MYC transgenic mice models, which overexpress MYC in lymphoid cells mostly develope T-cell lymphoma." (PMID 34372899, 2021). "Compared to ND tissue, all B-cell and one of two T-cell lymphomas exhibit higher protein expression of MYC and PRMT5." (PMID 33989303, 2021). "All members of the MYC protein family physically interact with the calcium sensor calmodulin in a Ca2+-dependent manner and in T-cell lymphoma, overexpressed MYC is stabilized by Ca2+/calmodulin-dependent protein kinase II γ (CAMKIIγ) phosphorylation." (PMID 31058089, 2019). "C-MYC (hereafter MYC) overexpression or rearrangements have been uncovered in different types of aggressive B cell or T cell lymphomas, and the MYC-miRNA-EZH2 oncogenic axis or loop has been demonstrated in several reports, including ours." (PMID 31752930, 2019). "Similar to our findings in the MYC model, IR-driven T cell lymphomas developed significantly later in Chk1+/− mice, suggesting a broader applicability of this phenomenon." (PMID 29167438, 2017). "In T cell lymphomas TCF3 exerts its tumor suppressing function by repression of proto-oncogenes MYC, CDK6 and by up-regulation of cell cycling inhibitor CDKN1A/p21, thereby leading to cell cycle arrest." (PMID 27166193, 2016). "Conditional overexpression c-Myc in hematopoietic cells in transgenic mice led to the formation of malignant T-cell lymphomas and acute myleoid leukemias, which were reverted by inactivation of the c-MYC transgene." (PMID 26472107, 2015). "Our results show that mice reconstituted with HSC overexpressing MYC developed myeloid leukemia and T cell lymphoma within 9 weeks, in agreement with previous reports." (PMID 22393362, 2012). "The interaction between RUNX3 and c-MYC has previously been investigated in T-cell lymphoma." (PMID 35069677, 2021). "Notably, deletion of Dnmt1 in an MYC-driven T-cell lymphoma model delayed lymphomagenesis and resulted in reduced proliferation of tumor cells." (PMID 33310759, 2021). "In contrast, c-MYC genetic alterations are rarely reported in T-cell lymphomas." (PMID 28379189, 2017). "In addition, Dnmt1 was shown to have cancer-specific de novo activity in a mouse model of MYC-induced T cell lymphomas, whereas Dnmt3a and Dnmt3b were primarily involved in maintenance methylation in tumors." (PMID 27690235, 2016). "However, a change in distribution of immature CD4+CD8+ versus mature CD4+ T-cell lymphoma was observed in MYC/FLIPL mice, possibly as a result of increased survival of the CD4+ population, but this did not significantly affect the outcome of the disease." (PMID 22393362, 2012). "However, while the ratio of AML versus T-cell lymphoma was not altered, the incidence of mature CD4+ T-cell lymphoma increased at the expense of immature CD4+/CD8+ T-cell lymphoma in MYC/FLIPL mice." (PMID 22393362, 2012). "Subsequently, we detected the expression of USP1, MAX and MYC in DLBCL, Burkitt and T cell lymphoma cell lines by using western blotting analysis, and found that the protein levels of USP1, MAX and MYC were high in RL-4RH cells." (PMID 36352191, 2023). "Taken together, the expression analysis indicates a direct correlation between MYC and DNMT3B expression levels in human B- and T-cell lymphoma." (PMID 29100357, 2017). "Any potential impact of FLIPL on MYC-induced B lymphomagenesis seems to be masked in this system by the rapid development of AML and T-cell lymphoma." (PMID 22393362, 2012). "One difference between MYC and MYC/FLIPL mice was that the ratio between immature CD4+/CD8+ and mature CD4+ T-cell lymphoma was skewed towards CD4+ lymphoma." (PMID 22393362, 2012). "Transplantation of HSCs expressing MYC into syngeneic recipient mice resulted in development of AML and T-cell lymphomas within 7–9 weeks as expected." (PMID 22393362, 2012).
T-cell lymphoma (continued). "In the other T-cell lymphomas, there was variable co-expression of EZH2 with pERK, MYC, and pSTAT3." (PMID 38339397, 2024). "In T-cell lymphoma, the MYC protein is overexpressed without MYC gene rearrangement or amplification but stabilized by Ca2+/calmodulin-dependent protein kinase II γ (CAMKIIγ) phosphorylation." (PMID 36969025, 2023). "Recently, it has been reported that MYC regulates the proliferation of aggressive mature T-cell lymphomas, ALCL, and peripheral T-cell lymphoma, not otherwise specified (PTCL-NOS)." (PMID 32587329, 2020). "We also analyzed MYC and MAX mRNA expression levels in other T-cell lymphomas compared with ALCL." (PMID 32587329, 2020). "Taken together, low MAX expression is specific for ALCL among T-cell lymphoma studied, regardless of MYC expression." (PMID 32587329, 2020). "Interestingly, lesions were positive for MYC (n=4), which has been shown previously to act cooperatively with RUNX2 to drive T-cell lymphoma." (PMID 24626992, 2014). "Mouse T-cell lymphomas show retroviral insertions at PVT1 and over-expression of PVT1 and one of PVT1's microRNA products and more retroviral insertions are seen at the PVT1 locus than at the MYC locus." (PMID 19419571, 2009). "Interestingly, MAX mRNA levels in ALCL were lower than those in other mature T-cell lymphomas, regardless of MYC expression." (PMID 32587329, 2020). "In particular, in our previous studies we observed upregulation of Dnmt3b in Dnmt3a-defficient MYC-induced T cell lymphomas, suggesting that such an event may result in aberrant de novo methylation." (PMID 27690235, 2016). "Similarly the targeting of novel genes that were not seen in previous large-scale screens of MoMLV-induced T-cell lymphomas (e.g. Otx2, Myo16) is not merely due to their up-regulation in the background of the Runx2/MYC model." (PMID 24586197, 2014). "In contrast to the effects of BCL-XL and BCL-2 overexpression, FLIPL although functional, did not enhance MYC-driven tumorigenesis, neither with respect to the kinetics nor the relative proportion of myeloid leukemia versus T cell lymphoma compared with MYC alone." (PMID 22393362, 2012). "In contrast, coexpression of MYC and FLIPL did neither accelerate tumorigenesis nor change the ratio of AML versus T-cell lymphoma." (PMID 22393362, 2012). "Coexpression of MYC and BCL-XL or BCL-2 strongly favored tumor development towards myeloid leukemia, whereas coexpression of MYC and FLIPL did not affect the distribution of myeloid versus lymphoid tumor cells, but changed the ratio between single CD4+ and double positive CD4+CD8+ T-cell lymphomas." (PMID 22393362, 2012).
thyroid cancer (51 papers, 2008 to 2026). "In a mouse model of ATC, high expression of the MYC gene was related to thyroid cancer progression as indicated by the loss of differentiation." (PMID 34761120, 2021). "It seems likely that other pathways / factors are associated with the increased mRNA levels and levels of MYC protein expression which have been documented to occur with increasing histologic aggressiveness and dedifferentiation in thyroid carcinomas." (PMID 28974238, 2017). "MYC, c-Myc-encoded protein, functions in cell proliferation and differentiation in several types of human cancers, including lung, breast, colon and thyroid cancers." (PMID 23527086, 2013). "However, in adult thyroid carcinoma we found that the top upregulated gene expression signatures are linked to proliferation and metabolism (MYC, and mTORC1 gene sets, highlighted in green)." (PMID 28350298, 2017). "A previous study found that Aurora-A binds to c-MYC in thyroid cancer, which partially explains the mechanism of its carcinogenic effect." (PMID 36990998, 2023). "Thyroid carcinomas arising through the effects of MYC overexpression include some papillary carcinomas, follicular carcinomas, poorly differentiated carcinomas, and anaplastic carcinomas." (PMID 34997561, 2022). "An oncogenic feature of NUT carcinomas also found in some thyroid carcinomas is MYC protein overexpression." (PMID 34997561, 2022). "DPT has been shown to inhibit cell proliferation through MYC repression and to be down-regulated in both oral and thyroid cancer." (PMID 34311724, 2021). "Another RNA of the miR-33a family, miR-33a-5p, is involved in the regulation of MYC expression in thyroid cancer." (PMID 34440124, 2021). "This RNA binds to the β-catenin-interacting protein CTNNBIP1, resulting in increased β-catenin activity and MYC gene expression in thyroid cancer cells." (PMID 34440124, 2021). "It has been reported that both SOX2 and c-MYC have anti-apoptotic effects in gastric, ovarian, head and neck and thyroid cancer cells." (PMID 33089188, 2020). "When MYC expression was blocked by antisense oligonucleotides, the proliferation of human thyroid cancer cell lines was inhibited." (PMID 30459933, 2018). "Among the genetic and epigenetic abnormalities recently identified in ATC, MYC was uncovered as a critical oncogene in promoting the development and progression of thyroid cancer." (PMID 30459933, 2018). "The evidence available in thyroid cancer confirms that c-MYC and SIRT1 are valuable therapeutic targets, encouraging translational researches aimed at the related pathways." (PMID 30319549, 2018). "cMYC expression was investigated in a spectrum of 94 follicular cell-derived thyroid carcinomas from 94 separate patients using an anti-MYC rabbit monoclonal antibody (Y69)." (PMID 28974238, 2017). "It is reported that Let-7 miRNA inhibited cell growth partially by decreasing mRNA expression of cell cycle stimulators MYC and cyclin D1 in thyroid cancer." (PMID 23806108, 2013). "Dermatopontin impeded the proliferation of thyroid cancer cells through MYC repression." (PMID 35723359, 2022). "In thyroid carcinomas, MYC overexpression develops by various means, including MYC amplification or rearrangements, BRAFv600e mutation interactions, specific long noncoding RNA dysregulation, increased BRD4 protein production, and abnormal TERT expression, among others." (PMID 34997561, 2022). "Several reports have demonstrated that abnormal expression of c-MYC may be related to increased m6A modification of its mRNA in several tumors as for example in thyroid cancer, or in oral squamous cell carcinoma (OSCC)." (PMID 34530916, 2021). "KAT5 enhances metastasis and invasion by stabilizing c-MYC in thyroid cancer." (PMID 34406978, 2021).
thyroid cancer (continued). "However, MYC expression was, to a lower extend, also observed in all other types of thyroid carcinoma, excluding this oncogene as a selective marker." (PMID 32719445, 2021). "In addition, the analysis of MAGEA3, as a second promising marker, and MYC, as a well-known upregulated gene in high-grade thyroid carcinoma, was considered to be included into the study." (PMID 32719445, 2021). "Therefore, MYC-driven AURKA signalling may constitute a positive feedback loop that helps to continuously activate the PI3K/AKT pathway in thyroid cancer." (PMID 36471438, 2022). "Then, IGF2BP2 was highly expressed in thyroid cancer, and MALAT1 was found to up-regulate IGF2BP2 and enhance MYC expression via m6A modification recognition by competitively binding to miR-204." (PMID 36281789, 2022). "In thyroid cancer, lncRNA HAGLR increases IGF2BP2 expression, and IGF2BP2 recognizes the m6A modification of c-MYC and leads to increased c-MYC expression, which promotes cancer progression." (PMID 35541906, 2022). "It changed the expression of several genes, with an increase in some genes that are abnormally expressed in thyroid cancer such as ATP-binding cassette subfamily G member 2 (ABCG2), c-Myc (MYC), and forkhead box protein A2 (FOXA2)." (PMID 34439207, 2021). "In thyroid cancer, JQ1 decreased MYC expression, induced cell cycle arrest, and suppressed tumor growth in a xenograft mouse model." (PMID 34761120, 2021). "The transcription of NTN1 and NTNG2 is positively regulated by MYC in THCA, suggesting that NTN1 and NTNG2 may also participate in the development of thyroid carcinoma." (PMID 32251318, 2020). "miR-323-3p targets one of the PDLIM family genes, out of which we have observed that PDLIM7 (Enigma) is upregulated in the same thyroid cancer tissues but not in benign tumors via the activation of MAPK and c-MYC (unpublished data)." (PMID 34590612, 2021).
adenoma (49 papers, 2001 to 2025). A neoplasm arising from the epithelium. "Compared to MYC or E2F-1 transgenic mice, double transgenic animals also showed potential cooperation between MYC and E2F-1 oncogenes, featuring a high frequency of β-catenin mutational activation and nuclear accumulation in both adenomas and carcinomas." (PMID 34771745, 2021). "The aim of the present study was to evaluate the prognostic role of the biomarkers CD133, AXL and c-MYC and their association with clinicopathologic characteristics in colorectal adenocarcinomas and adenomas, in a single institutional patient outcome." (PMID 33759958, 2021). "Evaluate the prognostic role of the biomarkers CD133, AXL and c-MYC and their association with clinicopathologic characteristics in colorectal adenocarcinomas and adenomas." (PMID 33759958, 2021). "Malignant transformation in the classical adenoma – carcinoma sequence is crucially associated with the activation of the Wnt/beta-catenin signaling pathway which leads to the transcriptional induction of the c-MYC oncogene." (PMID 23045412, 2012). "MYC activation profoundly accelerated lung tumor progression at every stage of adenoma evolution, triggering a precipitous drop in survival." (PMID 35309900, 2022). "In the mouse lung model of KRAS G12D-driven adenoma, it was found that coactivation of MYC would induce highly proliferative and invasive adenocarcinoma characterized by angiogenic and immunosuppressive stroma." (PMID 36185621, 2022). "The c-MYC oncogene was studied in a multiomics analysis of 275 patients pairing their normal colon tissue to the neoplastic tissue (from adenomas to UICC stage IV adenocarcinomas)." (PMID 33759958, 2021). "The authors concluded that global metabolic reprogramming of CRC occurs at the adenoma stage and is induced by MYC." (PMID 33759958, 2021). "Further study suggested that the level of c-MYC was correlated to the grade of differentiation of adenomas, as well as their size and malignant potentials." (PMID 34335790, 2021). "Avaliar o papel prognóstico dos biomarcadores CD133, AXL e c-MYC e sua associação com características clinicopatológicas de adenocarcinomas e adenomas colorretais." (PMID 33759958, 2021). "The results show clearly a significant increase in c-MYC mRNA level both in adenomas and carcinomas, thus validating our estimations of mRNA level." (PMID 25526641, 2014). "ApcMin/+ mice with transgenic PTGDS had fewer large adenomas (63% of control) and lower levels of v-myc avian myelocytomatosis viral oncogene homolog (MYC) mRNA in the colon." (PMID 24729479, 2014). "IRS1 mRNA and protein resulted higher, relative to paired mucosa, in adenomas of familial adenomatous polyposis patients and in CRCs that overexpressed c-MYC, ß-catenin, InsRß, and IGF1R." (PMID 22558377, 2012). "Induction of MYC in the lung epithelium by the administration of doxycycline in the drinking water of CM mice uniformly resulted in tumorigenesis that on histologic examination were consistent with adenomas or adenocarcinomas." (PMID 18461184, 2008). "Another immunohistochemical study was performed in 380 adenomas for differences in molecular Ki-67, COX-2, TGFβRI, EGFR, β-catenin, cyclin D1, c-MYC and TUNEL (apoptosis) mutations of proximal and distal adenomas, which may contribute for cancer heterogeneity between the two topographies." (PMID 33759958, 2021). "Unbiased analysis of the MYC targets V2 gene set revealed clusters correlated with the tumor histopathology, and adenocarcinoma-derived PDOs exhibited the high expression of distinct genes from adenoma-derived PDOs related to cellular proliferation, including CDK4, PLK1 and 4, MCM4, and MYC." (PMID 33060766, 2020).
adenoma (continued). "CMS2‐like adenomas exhibit enriched WNT and MYC signaling, while CMS1‐like adenomas are characterized by MSI and prominent immune infiltration." (PMID 39554798, 2024). "The coupling of oncogenic RAS to deregulated WNT leads to the formation of a large adenoma, as βcat/TCF4 and MYC are complemented by AP-1 of RAS." (PMID 35159051, 2022). "Microarranjos teciduais (TMA) dos tumores primários e adenomas foram realizados em busca de expressão de CD133, c-MYC e AXL, com posterior análise de relação significativa com características clinicopatológicas." (PMID 33759958, 2021). "For example, while the expression of SLC2A1 (GLUT-1) is higher in ACC than in NAG and adenomas and highest in the ACC-UMAP2 cluster, the expression of MYC for example is significantly lower in both ACC clusters when compared to the NAG." (PMID 34572898, 2021). "Four DEGs (MMP-7, MYC, WNT-5A, and AXIN2) were upregulated in tumor vs. normal tissues, or adenoma vs. normal tissue in TCGA, which was overlapped with our data." (PMID 32258125, 2020). "Although there were scant adenomas left for analysis from the combination treatment, the reduction of COX2, MYC, and BCL2 in the mebendazole only tumors also points to reduced inflammation beyond sulindac alone." (PMID 27612418, 2016). "Gene set enrichment analysis (GSEA) indicated that tumors derived from ISCs were characterized by high levels of MYC and WNT signaling, whereas PC-derived adenomas showed higher levels of inflammatory pathways indicative of infiltration from the tumor microenvironment (TME)." (PMID 38902475, 2024). "In hyperplastic polyps and sessile serrated adenomas without intraepithelial neoplasia c-MYC expression was mainly localized to one or two thirds of the base of the crypts, corresponding to a low or moderate expression in the majority of cases (51 of 54 cases (94%))." (PMID 23045412, 2012). "In the adenoma group, no statistically significant expression or correlation with patient outcome data were found for the biomarkers CD133, c-MYC and AXL." (PMID 33759958, 2021). "In the univariate analysis, there was no statistical significance between CD133+, c-MYC+ and AXL+ adenomas and size, anatomic location, type, histological diagnosis and status of dysplasia." (PMID 33759958, 2021). "Notably, the copy number gains of both MYC and LZTR1 were particularly pronounced in the SC-NEC (MYC: 25.0, LZTR1: 56.16) and sarcomatoid areas (MYC: 29.02, LZTR1: 58.18) compared to the adenocarcinoma (MYC: 14.3, LZTR1: 22.88) and adenoma (MYC: 10.13, LZTR1: none) compartment." (PMID 40833530, 2025).